U6 (U6 spliceosomal RNA )
Synonyms: LOC124903275
Gene: Small nuclear RNA gene on chromosome 13 (18,418,526 to 18,418,632, forward strand). Ensembl gene ENSG00000276183.
Gene Ontology:
Molecular function: U4 snRNA binding
Biological process: formation of quadruple SL/U4/U5/U6 snRNP; spliceosomal tri-snRNP complex assembly
Cellular component: U4/U6 x U5 tri-snRNP complex; U6 snRNP
Homologues: Orthologues: chimpanzee U6 (99% identical), macaque U6 (89% identical), dog U6 (63% identical), rabbit U6 (62% identical), pig U6 (61% identical), rabbit U6 (59% identical). Paralogues in human: RNU6-614P (99% identical), RNU6-1132P (97% identical), RNU6-1293P (95% identical), RNU6-156P (95% identical), RNU6-721P (95% identical), RNU6-458P (94% identical), U6 (94% identical), RNU6-1207P (90% identical), RNU6-811P (90% identical), RNU6-978P (90% identical), RNU6-452P (85% identical), RNU6-666P (84% identical), and 1287 more.